TLR4 (toll like receptor 4)
Diseases named in the same sentence as TLR4 in open-access papers (continued):
Sharing a sentence is not in itself a finding about the gene and the disease.
colorectal cancer (194 papers, 2008 to 2026). A primary or metastatic malignant neoplasm that affects the colon or rectum. "In colorectal cancer, PD‐L1 expression was significantly associated with TLR4, with high levels of both correlating with poor disease‐free survival." (PMID 40762187, 2025). "Reducing IL-6 and TNF-α expression and infiltration of pro-inflammatory macrophages, remodeling gut microbiota composition and bile acid metabolism to inhibit the TLR4/MyD 88 pathway, and thereby inhibiting colorectal cancer associated with a high-fat diet." (PMID 40066456, 2025). "While previous studies have revealed that TLR4 expression is significantly associated with tumor progression, including colorectal cancer, head and neck cancer and ovarian cancer." (PMID 35372062, 2022). "In line with our observations, TLR4 polymorphisms on PBMCs were more frequently detected in metastatic than early colorectal cancer (CRC) patients." (PMID 35205801, 2022). "Recently, a significant association of variant alleles of the TLR4 rs4986790 and rs4986791 with the risk of development of colorectal cancer was reported by a study that included 268 subjects (127 patients and 141 healthy Egyptians)." (PMID 35330409, 2022). "The role of dysbiosis-associated TLR4-signaling in the pathogenesis of colorectal cancer was also reported were TLR4 under the influence of protease cathepsin K, triggers M2 polarization of macrophages and promotes tumor metastasis." (PMID 35625485, 2022). "Contrary to our observation, the haplotype analysis of TLR4 SNPs, (namely AT and GT haplotypes) were associated with increased odds for colorectal cancer (OR = 3.54 and 3.45; 95% CI: 1.48–8.48 and 1.09–10.83, respectively)." (PMID 35330409, 2022). "Strong expression of TLR4 in tumors of colorectal cancer patients has been associated with poor prognosis." (PMID 34025672, 2021). "Distribution of TLR-4 SNPs genotype and allele frequencies in colorectal cancer cases and control population based on gender (Female)." (PMID 26771524, 2016). "Distribution of TLR-4 SNPs genotype and allele frequencies in colorectal cancer cases and control population based on gender (Male)." (PMID 26771524, 2016). "Distribution of TLR-4 SNPs genotype and allele frequencies in colorectal cancer cases and control population based on age (≤ 50 years)." (PMID 26771524, 2016). "At difference with breast or colorectal cancer, a loss-of-function allele of toll like receptor 4 (TLR4) improved cancer-specific survival of patients with esophageal cancer." (PMID 26369701, 2015). "Even a loss of functional TLR4 allele was found linked with decreased survival in colorectal cancer patients treated with oxaliplatin-based chemotherapy." (PMID 29147386, 2014). "In both mouse and human colorectal cancer TLR4 is over expressed, and mice deficient in TLR4 are insensitive to colon cancer." (PMID 25152696, 2014). "The present study examined the impact of two common polymorphisms of the TLR4 genes on the response of the HCT116 colorectal cancer cells to 5-FU." (PMID 24250621, 2013). "mRNA of colorectal carcinoma cell lines encoding TLR4 with its co-molecules, MD-2 were determined using RT-PCR." (PMID 22180778, 2011). "Notably, the TLR4 9:117713042 variant represents a novel finding in colorectal cancer, located near the well-studied rs4986790 (Asp299Gly) polymorphism on exon 3, suggesting potential functional significance that warrants further investigation." (PMID 40703545, 2025). "TLR4/MyD88/NF-κB signaling pathway is a well-known pathway related to immune inflammatory responses and its activation is associated with multiple diseases, such as knee osteoarthritis, ulcerative colitis, and colorectal cancer." (PMID 31885500, 2019). "Additionally, TLRs have been demonstrated to play a role in the progression of polyps to tumors, and reduced TLR4 expression has been associated with the increased metastasis potential of colorectal cancer (CRC)." (PMID 26771524, 2016).
colorectal cancer (continued). "Nowadays, many candidate genes have been identified, such as toll-like receptor 4 (TLR-4), which may be implicated in the genesis of colorectal cancer." (PMID 24705379, 2014). "Meta-analysis of the associations between TLR-4 genetic polymorphisms and colorectal cancer risk." (PMID 24705379, 2014). "Toll-like receptors (TLRs), particularly TLR1, TLR2, and TLR4, play a multifaceted role in the progression of colorectal cancer (CRC)." (PMID 41419456, 2025). "This study establishes three key findings regarding TLR4/MyD88 pathway alterations in colorectal cancer." (PMID 40703545, 2025). "In a colorectal cancer model, toll-like receptor 4 (TLR4) was shown to promote cell proliferation, migration, and invasion by increasing ACAT1 expression in HT29." (PMID 39940954, 2025). "Toll-like receptor 4 (TLR4) and myeloid differentiation factor 88 (MyD88) signaling play a critical role in colorectal cancer (CRC) development." (PMID 40703545, 2025). "This aligns with Xianjing Hu and colleagues' study wherein palmitic acid modulates TLR4 expression in a PU.1-dependent manner, adjusting cancer metabolism in colorectal cancer under high-fat dietary conditions." (PMID 39979806, 2025). "For instance, LPS has been shown to enhance cell adhesion and invasion by activating TLR4 signaling in colorectal cancer." (PMID 40666174, 2025). "Our comprehensive analysis of TLR4/MyD88 pathway in colorectal cancer reveals three key findings that advance our understanding of inflammatory signaling in colorectal carcinogenesis." (PMID 40703545, 2025). "Research indicates that Fusobacterium nucleatum (F. nucleatum) activates the autophagy pathway in colorectal cancer (CRC) cells via the TLR4 and related (TLR4/Keap1/NRF2, TLR4/NF-κB/S100A9, TLR4/ROS, NOD1/2, TLR4/P-PAK1) signaling pathways." (PMID 39342061, 2025). "Pancreatic, liver, breast, gastric, and colorectal cancers are among the cancer types where LPS acts as the primary activator of TLR4." (PMID 40666174, 2025). "Our study revealed distinct expression patterns of TLR4/MyD88 in colorectal cancer compared to adenomas, with several important implications for understanding CRC pathogenesis." (PMID 40703545, 2025). "F. nucleatum activates the β-catenin pathway by increasing the expression of TLR4 and P-PAK1 proteins, the latter being associated with metastatic progression of colorectal carcinomas." (PMID 40927726, 2025). "It facilitated the Polarization of M2 macrophage and increased the progression of colorectal carcinoma via inducing TLR4/NF-κB/S100A9 Cascade." (PMID 41326479, 2025). "RETN binds to toll-like receptor 4 (TLR4) on the surface of colorectal cancer cells, switching on ERK signaling." (PMID 39839775, 2024). "Actinomyces has been shown to the production of various immunological and microbial-related genes, such as TLR2, TLR4, and NF-B, which support the growth of colorectal cancer by controlling inflammation by activating the downstream TLR4/NF-B pathway." (PMID 38445094, 2024). "In ovarian and colorectal cancer cell lines, the activation of TLR-4 by lipopolysaccharides (LPS) upregulates Gal-1 expression through the PI3K/AKT pathway, consequently promoting EMT." (PMID 38570874, 2024). "In colorectal cancer cells, activation of TLR4 can lead to the activation of the nuclear transcription factor nuclear factor of activated T cells 5 (NFAT5), which in turn promotes the expression of JmjC-domain-containing histone demethylase 2B (JMJD2B)." (PMID 38523155, 2024). "Parabacteroides has been suggested to have anticancer effects in mouse models of colorectal cancer through suppression of TLR4 and AKT signaling." (PMID 38280026, 2024). "Microbiota has been shown to promote colorectal cancer metastasis by stimulating cathepsin K secretion and mediating TLR4-dependent M2 macrophage polarization." (PMID 38890429, 2024).
colorectal cancer (continued). "TLR4 is critical in microbial pattern recognition and is overexpressed in colorectal cancers and adenomas compared to healthy tissues in humans." (PMID 39148929, 2023). "For example, gut dysbiosis-stimulated cathepsin K secretion mediated TLR4-dependent M2 macrophage polarization and promoted tumor metastasis in colorectal cancer." (PMID 37743857, 2023). "CT26 HA is a kind of expression of colon cancer cells, CD44 and TLR4 CRISPR knockout CT26 colorectal cancer cell was relatively slow growth, this suggests the HA combination of CD44 and TLR4 promote CT26 homologous grafts of tumor growth." (PMID 37020597, 2023). "Realtime-PCR and western blot were used to explore toll-like receptor 4 (TLR4) expression in colorectal cancer cell lines." (PMID 36647071, 2023). "The TLR4 positive colorectal cancer cells demonstrated a higher chemotherapy resistance potential than TLR4 negative colorectal cancer cells." (PMID 36647071, 2023). "The functions of TLR4 in the stemness of the colorectal cancer cell lines were analyzed by infecting cells with lentivirus containing TLR4 siRNA." (PMID 36647071, 2023). "In recent years, enhanced TLR4 expression was identified in several tumors, including pancreatic cancer, colorectal cancer, and esophageal cancer, among others." (PMID 35464826, 2022). "Subsequently, inhibition of TLR4 activity remarkably reduced the viability of colorectal cancer cells, which was abolished upon TLR4 overexpression." (PMID 35955525, 2022). "Contrarily, Fusobacterium nucleatum increased the proliferation of colorectal cancer cells via activating the Toll-like receptor 4 signaling to NF-κB and miR21." (PMID 35596224, 2022). "A study in a rat model of colorectal cancer evaluated the effect of administering toll-like receptor 4 (TLR4) lipopolysaccharide (LPS) or toll-like receptor 5 (TLR5) agonist flagellin after radiation." (PMID 36230500, 2022). "Studies have found that baicalein can target TLR4/HIF-1α/VEGF signaling pathway in the treatment of colorectal cancer." (PMID 36415861, 2022). "One such gene, TLR4 is a major player in innate immunity and several studies correlated its role with colorectal carcinoma earlier." (PMID 35486660, 2022). "For instance, it has been shown that infection with F. nucleatum enhanced M2 polarization of macrophages through TLR-4 activation, which increased tumor growth in colorectal cancer." (PMID 35008213, 2021). "Numerous studies have shown that TLR4 overexpresses in colon mucosa of colorectal cancer patients, but TLR4 knockout mice can significantly reduce the incidence rate of colon cancer." (PMID 34249260, 2021). "The aim of our study was to investigate the interplay between MMR genes and TLR4 expression in colorectal cancer." (PMID 34026821, 2021). "As a potential anti-inflammatory target, BMI1 regulates invasion and EMT of colorectal cancer cells via TLR4/MD-2 MyD88 complex-mediated NF-κB signaling pathway." (PMID 33927214, 2021). "TLR4 is overexpressed in colorectal cancer (CRC), and is directly correlated with the survival of the patients." (PMID 34385421, 2021). "Colorectal cancer tissues usually have higher TLR2 gene expression levels than normal colorectal mucosa from the same patient, and activation of TLR2 and TLR4 in previous studies of colorectal cancer has also been shown to promote tumor cell proliferation." (PMID 32256204, 2020). "For example, F. nucleatum activates autophagy-related pathways in colorectal cancer through modulation of TLR4 and MYD88 innate signaling, along with certain miRNAs which subsequently promote chemoresistance." (PMID 33197886, 2020). "Apoptosis induction observed after TLR4 downregulation in both colorectal cancer cells confirmed previous studies describing the major role of TLR4 in apoptosis resistance and in colon cancer cell survival." (PMID 32322173, 2020).
colorectal cancer (continued). "TLR4 blockade using neutralizing anti-TLR4 antibody confirmed this induction of apoptosis in both colorectal cancer HT29 and SW620 cells and revealed to be enhanced by the presence of HM, as compared with untreated cells, the control." (PMID 32322173, 2020). "This study aimed to explore the prognostic value of TLR2 and TLR4 tumor expressions in colorectal cancer patients." (PMID 32424768, 2020). "By querying GENT2 datasets, we identified the gene expression level of TLR2 and TLR4 as being substantially increased in colorectal cancer." (PMID 32050430, 2020). "Expression of TLR2 or TLR4 mRNA is higher in patients’ tumor samples, which was suggested to be a marker in human colorectal cancer." (PMID 32050430, 2020). "Among all the TLRs, expression of TLR2 and TLR4 mRNA is increased significantly in colorectal cancer based on the bioinformatics analysis in the GENT2 database." (PMID 32050430, 2020). "Altogether, these findings indicate that HM exerts pro-apoptotic effects and inhibits MAPK pathway through TLR4 in mCRC and colorectal adenocarcinoma cells, suggesting HM as a promising natural-based drug for the treatment of colorectal cancer." (PMID 32322173, 2020). "In previous studies, Xie and colleagues verified that LPS promoted the proliferation and invasive ability of colorectal cancer cells by activating TLR4/p65-NF-κB in an inflammatory environment." (PMID 32014008, 2020). "We found that exosomes released by all cell lines analyzed express on their surface MICA/B, a NKG2D ligand, although only in colorectal cancer cells-derived exosomes TLR4 activation increased its expression." (PMID 31186484, 2019). "Constitutional loss of function (LOF) single nucleotide polymorphisms (SNPs) in pattern recognition receptors FPR1, TLR3, and TLR4 have previously been reported to predict oxaliplatin benefit in colorectal cancer." (PMID 30649440, 2019). "TLR4 as a receptor of LPS has been detected in many human cancer cell lines, including pancreatic, liver and colorectal cancer." (PMID 29308184, 2018). "The aim of this study was to investigate TLR2 (-196 to-174del), TLR4 (Asp299Gly and Thr399Ile) and TLR9 (T1237C and T1486C) gene polymorphisms at risk of colorectal cancer (CRC) development and progression." (PMID 29883450, 2018). "Via binding to TLR4 on colorectal cancer cells, Fusobacterium nucleatum activated the TLR4/MYD88 innate immune signaling pathway and miRNA-18a and miRNA-4802 were downregulated sequentially, which resulted in ULK1 and ATK7 expression." (PMID 30374420, 2018). "The increased TLR4 levels have been correlated with poor prognosis in patients with gastric, prostate and colorectal cancer, although the results are still controversial." (PMID 29883450, 2018). "Single nucleotide polymorphisms (SNPs) in TLR2 and TLR4 have been associated with childhood asthma, chronic obstructive pulmonary disease (COPD) and colorectal cancer." (PMID 27307950, 2016). "Colorectal cancer cells are likely to be exposed to bacterial LPS, derived from the gut microbiota, which is known to activate NF-κB via Toll-like receptor 4 (TLR4)." (PMID 25978030, 2015). "TLR4 is dysregulated in many human cancers, such as gastric cancer, colorectal cancer, and non-small cell lung cancer (NSCLC)." (PMID 26514586, 2015). "In 25 positive cases of IE1–72, there were 24 positive cases of TLR2 and 24 positive cases of TLR4 in the colorectal cancer samples." (PMID 25435993, 2015). "In contrast, constitutively active TLR4 was found to reduce tumor load in an APC (Min/+) mouse model of colorectal carcinoma through induction of apoptosis." (PMID 26514586, 2015). "Studies have shown the significance of TLR4 expression in pancreatic ductal adenocarcinoma and its correlation with poor prognosis in colorectal cancer." (PMID 25299052, 2014). "In conclusion, 5-FU-induced TLR4 expression and LPS had synergistic effect with 5-FU to induced apoptosis in colorectal cancer cells." (PMID 24250621, 2013).
colorectal cancer (continued). "Using immunofluorescence directed to TLR4, we found that a third of sporadic human colorectal cancers over-express this marker." (PMID 23691015, 2013). "Their findings suggest that TLR4/MyD88 signaling promotes colorectal cancer progression by contributing to liver metastasis." (PMID 22985132, 2012). "Nevertheless, little else is known of the involvement of TLR4 in the progression of colorectal carcinoma." (PMID 22180778, 2011). "In summary, we have shown that the alteration of CXCR7 expression mediated by TLR4 promotes tumor cell proliferation and migration in human colorectal carcinoma." (PMID 22180778, 2011). "On the contrary other studies concerning colorectal carcinoma showed correlation between reduced TLR4 expression and increased metastatic potential of the tumor." (PMID 22110526, 2011). "Our data showed a marked increase of CXCR7 expression in a TLR4/MD-2 positive colorectal carcinoma SW480 and Colo 205 cell lines in response to LPS." (PMID 22180778, 2011). "To demonstrate the role of TLR4 signalling in colon tumourigenesis, we examined the expression of TLR4 and myeloid differentiation factor 88 (MyD88) in colorectal cancer (CRC)." (PMID 20145615, 2010). "People have reported that TLR4 is an important member of TLRs and has been shown to be present in tumors, such as ovarian cancer, prostate cancer cell and colorectal cancer cell." (PMID 20618976, 2010). "This correlates with the protection from AOM induced colorectal cancer in TLR4-/-mice, suggesting that TLR4 signaling plays a role in CRC progression." (PMID 21059221, 2010). "Furthermore, enterotoxigenic B. fragilis activates Toll-like receptor 4 (TLR4) in colorectal cancer cells, upregulating JMJD2B expression through the TLR4-NFAT5-dependent signaling pathway." (PMID 41399387, 2026). "Fusobacterium nucleatum has been reported to activate the TLR4-mediated autophagy pathway in colorectal cancer cells, which may contribute to drug resistance." (PMID 40299650, 2025). "Additionally, F. nucleatum increases proliferation of colorectal cancer cells and tumor development in mice by activating toll-like receptor 4 signaling (TLR4) to nuclear factor -κB (NF-κB), and up-regulating expression of microRNA-21." (PMID 41158778, 2025). "Similarly, in colorectal cancer, restoring TLR4 expression was observed to reverse the inhibitory action of miR-5195-3p upregulation on cancer cell activity." (PMID 40999508, 2025). "Our findings suggest potential future research directions for TLR4/MyD88 pathway modulation in colorectal cancer, though extensive functional validation and clinical studies would be required before any therapeutic applications could be considered." (PMID 40703545, 2025). "Moreover, the D299G mutation is associated with higher tumor grades and increased metastasis rates, underscoring the pivotal role of TLR4 mutations and CHI3L1 upregulation in colorectal cancer development and progression." (PMID 40260255, 2025). "In this review, we search the PubMed database using the keywords “TLR4” and “Colorectal cancer”." (PMID 38930793, 2024). "In colorectal cancer cells treated with NETs, NE activated TLR4, promoting tumor growth." (PMID 38201433, 2023). "Aspirin lead to down-regulation of TLR4 expression of colorectal cancer cells." (PMID 36647071, 2023). "We further demonstrated aspirin could promoted the chemosensitivity of colorectal cancer cell by suppressing the stemness of CRC cells via downregulating the expression of TLR4." (PMID 36647071, 2023). "Besides that, we found that aspirin lead to down-regulation of TLR4 expression of colorectal cancer cells." (PMID 36647071, 2023). "Also, flow cytometry studies revealed an increase in the surface expression of TLR4 upon LPS stimulation (1 μg·mL−1) in different colorectal cancer cell lines." (PMID 34689394, 2022).